RN7SL131P (RNA, 7SL, cytoplasmic 131, pseudogene)
Gene: Miscellaneous RNA gene on chromosome 1 (36,191,915 to 36,192,170, forward strand). Ensembl gene ENSG00000264592.
Homologues: Orthologues: macaque Metazoa_SRP (84% identical), macaque Metazoa_SRP (83% identical), macaque Metazoa_SRP (82% identical), chimpanzee Metazoa_SRP (78% identical). Paralogues in human: RN7SL510P (87% identical), RN7SL96P (87% identical), RN7SL774P (86% identical), RN7SL811P (86% identical), RN7SL391P (86% identical), Metazoa_SRP (85% identical), RN7SL123P (85% identical), RN7SL163P (85% identical), RN7SL134P (84% identical), RN7SL470P (84% identical), RN7SL474P (84% identical), RN7SL596P (84% identical), and 709 more.